KL (klotho)
Diseases named in the same sentence as KL in open-access papers (continued):
Sharing a sentence is not in itself a finding about the gene and the disease.
diabetic nephropathy (continued). "The authors did not identify significant relationships between micro- and macro-vascular diabetes complications and s-Klotho concentrations, with the exception of diabetic nephropathy." (PMID 35286490, 2022). "Klotho attenuates diabetic nephropathy in db/db mice and ameliorates high glucose-induced injury of human renal glomerular endothelial cells." (PMID 35692408, 2022). "Such research not only demonstrates the role of MALAT1 in devising the chromatin status of klotho but implies the prospect of targeting MALAT1 to ameliorate glomerular EC function in hyperglycaemia to impede the progression of diabetic nephropathy." (PMID 34698214, 2021). "Targeting other signaling pathways that are inhibited by Klotho has shown promising results with regard to improving health in patients with DM and diabetic nephropathy." (PMID 33478014, 2021). "Recent evidence suggest that soluble klotho plays a renoprotective role in the experimental models of diabetic nephropathy." (PMID 33891667, 2021). "It was demonstrated that MALAT1 was upregulated in patients with diabetic nephropathy and inversely correlated with the expression of klotho—a gene known to improve the function of hyperglycaemia (HG)-induced glomerular EC injury." (PMID 34698214, 2021). "Klotho protects cells against accelerated aging and damage during the course of DM and diabetic nephropathy." (PMID 33478014, 2021). "The expression of Klotho protein is downregulated in early stages of inflammation and diabetic nephropathy by proinflammatory factors." (PMID 33478014, 2021). "In many studies, a renal klotho expression is decreased in experimental animal models and in the patients with diabetic nephropathy, and plasma soluble klotho is negatively correlated with the progression of nephropathy with type 2 diabetic patients." (PMID 33891667, 2021). "In this regard, in a mice model of diabetic nephropathy, Klotho seems to protect glomerular and podocyte injury by inhibiting glomerular hypertrophy and reducing albuminuria." (PMID 32188018, 2020). "In diabetic nephropathy, Klotho is also reported to protect from glomerular hypertrophy in a cell cycle-dependent manner." (PMID 33162804, 2020). "To analyze the relationship between Klotho and phenotypes of diabetic nephropathy, we carried out in vivo experiments." (PMID 33162804, 2020). "Atrasentan increased the expression of klotho by mediating miR-199b-5p and prevented renal tubular injury in diabetic nephropathy." (PMID 26813039, 2016). "Lower serum Klotho levels are also often observed in diabetic subjects, and this is particularly obvious in the presence of diabetic nephropathy when renal function has deteriorated." (PMID 27668003, 2016). "Furthermore, in the context of diabetic kidney disease, extracellular vesicles from albumin-treated tubular epithelial cells were found to induce M1 polarization through miR-199a-5p, which targets Klotho—a critical modulator of inflammation." (PMID 40534860, 2025). "Therefore, podocytes are considered to be the ‘ weak link ‘ in the progression of diabetic nephropathy.In this pathological context, the role of Klotho is gradually revealed." (PMID 41438297, 2025). "Furthermore, epigenetic research has discovered that N6‐methyladenosine (m6A) modification in the Klotho gene suppresses Klotho expression and increases inflammation and kidney damage in diabetic kidney disease." (PMID 40119098, 2025). "This shows that Klotho has a protective effect on the early structural damage of diabetic nephropathy, and may delay the progression of the disease by maintaining the integrity of podocytes." (PMID 41438297, 2025). "In addition, participants in the higher serum Klotho quartiles was found to have higher eGFR compared to those in the lower serum Klotho quartiles, as previously reported in populations with diabetic nephropathy (DN)." (PMID 36440221, 2022).
diabetic nephropathy (continued). "Besides, both in vitro and in vivo evidence have demonstrated that Klotho can attenuate diabetic nephropathy and cardiomyopathy, indicating the cardio-renal protective effects of Klotho." (PMID 36440221, 2022). "Soluble alpha KL has emerged as a potential marker of early diabetic nephropathy." (PMID 35992154, 2022). "Therefore, IL-6 appears to be an important factor in the development of a local inflammatory response in the kidneys in diabetic nephropathy, which is counteracted by calcitriol and Klotho protein." (PMID 33478014, 2021). "This might contribute to the decrease in the expression of functional Klotho protein also in diabetic nephropathy." (PMID 33478014, 2021). "Thus, the current study aims to investigate the renoprotective effects of klotho against podocyte injury in diabetic nephropathy." (PMID 33891667, 2021). "Similarly, the lower expression of MCP-1 and ICAM-1, which are inhibited by Klotho, reduced the accumulation of macrophages in the kidneys in animals with diabetic nephropathy and decreased tubulointerstitial injury after PKC-β inhibition by ruboxistaurin." (PMID 33478014, 2021). "Low levels of Klotho mRNA and protein were also expected to be observed in diabetic nephropathy." (PMID 33478014, 2021). "Meanwhile, it has been shown that downregulation of klotho could accelerate the progression of diabetic kidney disease via promoting M1 polarization." (PMID 32464602, 2020). "Finally, a reduction in renal Klotho gene expression has been observed in kidneys from patients with diabetic nephropathy." (PMID 23945089, 2013). "This view elevates the research of Klotho from “ passive association “ to “ core link of pathological mechanism, “ and also means that if effective Klotho derivatives or up-regulation can be developed, it may fundamentally interfere with the occurrence and development of diabetic nephropathy." (PMID 41438297, 2025). "The transcription of Klotho is downregulated in response to pro-inflammatory conditions, angiotensin II, nuclear factor κ light chain enhancer of activated B cells (NF-κB) signalling, matrix metalloproteinases and certain conditions such as dehydrated states and diabetic nephropathy." (PMID 38213484, 2024). "However, the renoprotective effect of klotho in lipotoxicity-induced obese diabetic kidney disease remains unclear." (PMID 33891667, 2021). "However, the effects of klotho on podocyte injury in diabetic nephropathy are poorly understood." (PMID 33891667, 2021). "We investigated if sKlotho levels are decreased in type 2 diabetes and associate with MVD in the absence of diabetic nephropathy, and whether hyperglycemia affects renal Klotho production in vitro and in vivo." (PMID 23945089, 2013). "The exogenously supplemented Klotho in cultured kidney cells suppressed TNF-α stimulation and NF-κB activation, thereby minimizing kidney damage and mitigating the advancement of diabetic kidney disease." (PMID 40119098, 2025). "Albumin-stimulated renal tubular epithelial cells induce macrophage M1-type polarization by releasing extracellular vesicles (EVs) containing miR-199a-5p, which targets the Klotho/TLR4 pathway and accelerates diabetic nephropathy progression." (PMID 39308872, 2024). "In cultured macrophages, Klotho suppressed the lipopolysaccharide (LPS)-induced activation of NF-κB by upregulating HSP70 levels, which are elevated in diabetic nephropathy kidney tissue." (PMID 33478014, 2021). "In conclusion, this research provides evidence that NEAT1 is involved in the protective effect of Klotho against renal tubulointerstitial fibrosis and EMT in renal tubular epithelial cells through the ERK1/2 signaling pathway in diabetic kidney disease." (PMID 32054986, 2020). "However, although some studies have shown that dual blockade therapy for diabetic nephropathy RAAS is superior to monotherapy, the relationship between this benefit and klotho is unclear." (PMID 37143722, 2023).
diabetic nephropathy (continued). "This is supported by the co-expression of Klotho and TRPM6 in distal tubular cells, and by the fact that the renal expression of Klotho and TRPM6 are strongly correlated in healthy individuals as well as in patients with diabetic nephropathy." (PMID 36699036, 2022). "The fibrotic process in the kidneys in patients with diabetic nephropathy may also be induced by TGF-β1 and the Wnt/β-catenin pathway, both of which are inhibited by Klotho." (PMID 33478014, 2021). "The correlation between Klotho and NEAT1 provides novel insight into the mechanism by which Klotho may be used to treat diabetic kidney disease." (PMID 32054986, 2020). "In 109 patients with diabetic nephropathy, pulse wave velocity (PWV) was reported to increase in those with CKD but was not related to serum klotho concentration." (PMID 33504927, 2021). "Another cross-sectional cohort study that included 172 patients with early diabetic kidney disease, showed a statistically significant negative correlation between serum Klotho levels and pulse wave velocity (PWV), emphasizing the effect of serum Klotho levels on aortic wall stiffness." (PMID 39329104, 2024).
endothelial dysfunction (58 papers, 2012 to 2025). In vascular diseases, endothelial dysfunction is a systemic pathological state of the endothelium (the inner lining of blood vessels) and can be broadly defined as an imbalance between vasodilating and vasoconstricting substances produced by (or acting on) the endothelium. "Klotho deficiency leads to endothelial dysfunction, arterial stiffness, hypertension, and impaired angiogenesis, while high plasma levels reduce the risk of cardiovascular diseases, including stroke." (PMID 41002407, 2025). "Elevated FGF23 and reduced Klotho levels have been linked to arterial stiffness, vascular calcification, and endothelial dysfunction." (PMID 41516280, 2025). "In DKD, Klotho levels are often reduced, which is associated with increased oxidative stress, endothelial dysfunction, and accelerated progression of both renal and cardiovascular disease." (PMID 39765800, 2024). "Recent studies have shown that Klotho protects the vascular system, including endothelial homeostasis and vascular functionality, and that loss of klotho contributes to endothelial dysfunction and vascular calcifications." (PMID 35307922, 2022). "Given that a single bout of resistance‐exercise‐induced hypertensive stimulus causes endothelial dysfunction, we postulated that acute resistance exercise would reduce serum Klotho levels." (PMID 34713986, 2021). "Previous experimental studies in animal models have shown that Klotho deficiency causes disruptions in endothelial homeostasis, further leading to endothelial dysfunction, which is a critical factor in the pathogenesis of AS." (PMID 32138681, 2020). "Despite this, the functional KL-VS variant of the KLOTHO gene protects against the development of retinopathy in patients with T1D and is likely to improve inflammatory status and delay endothelial dysfunction in these subjects." (PMID 32435919, 2020). "Previous studies showed a complex syndrome in Klotho-deficient mice in which two remarkable changes are arteriosclerosis and endothelial dysfunction." (PMID 30547758, 2018). "In contrast, many studies indicated that decreased NO is another key mechanism underlying endothelial dysfunction, which is interrelated with decreased expression of the Klotho gene." (PMID 28407763, 2017). "It is known that higher FGF-23 concentrations are associated with reduced expression of the co-receptor Klotho, as the cause of endothelial dysfunction." (PMID 26462160, 2015). "Similarly, endothelial dysfunction in heterozygous Klotho-deficient mice is prevented by parabiosis with wild-type mice." (PMID 37274332, 2023). "Moreover, KLOTHO deficiency causes inflammation, endothelial dysfunction, and vascular calcification." (PMID 32435919, 2020). "As KL-VS haplotype alters secretion and activity of KLOTHO and UA is associated with endothelial dysfunction and inflammation, their mutual links may contribute to microalbuminuria in patients with T1D." (PMID 32435919, 2020). "As the KL-VS haplotype alters secretion and activity of KLOTHO and uric acid (UA) is associated with endothelial dysfunction and inflammation, their mutual links may contribute to microalbuminuria (MA) in patients with type 1 diabetes (T1D)." (PMID 32435919, 2020). "Decreased klotho protein expression possibly associated with vascular calcification and endothelial dysfunction, which might contribute to cerebrovascular disease." (PMID 30791885, 2019). "Thus, it is possible to speculate that the allele A variant of the G‐395A Klotho gene is associated with lower vascular Klotho expression, which would promote the development of endothelial dysfunction." (PMID 26538295, 2016). "Growing evidence links them to molecular and vascular ageing, including oxidative stress, endothelial dysfunction, and reduced expression of longevity-related proteins like Klotho and SIRT1." (PMID 41002407, 2025).
endothelial dysfunction (continued). "Recent studies indicate a link between these conditions and endothelial dysfunction, oxidative stress, mitochondrial dysregulation, and altered expression of key longevity regulators such as Klotho and SIRT1." (PMID 41002407, 2025). "Elevated phosphate further exacerbates vascular calcification and endothelial dysfunction via the FGF23/Klotho axis and PTH-mediated pathways." (PMID 41166265, 2025). "These factors include endothelial dysfunction, oxidative stress, inflammation, and abnormalities in glucose and lipid metabolism, serving as potential target points for the effects of Klotho." (PMID 40369033, 2025). "Preclinical studies on Klotho-knockout mice revealed extensive vascular calcification, endothelial dysfunction, and progressive atherosclerosis." (PMID 40369033, 2025). "Conversely, Klotho proteins have been demonstrated to alleviate endothelial dysfunction by inhibiting the ROS/p38MAPK and downstream NF-κB signaling pathways." (PMID 38907289, 2024). "In Klotho defective mice, research has indicated a reduction in NO production, endothelial dysfunction, and arteriosclerosis." (PMID 35509269, 2022). "In that study, serum Klotho stimulated endothelium-derived NO production, which ameliorated endothelial dysfunction and prevented vascular remodeling." (PMID 34354161, 2021). "Importantly, experimental models point to the existence of Klotho protective effects upon vascular system that include the maintaining of endothelial wall homeostasis and the promotion of vascular health, whereas Klotho deficiency triggers endothelial dysfunction and vascular calcification." (PMID 34354161, 2021). "Klotho protein (Clotho; HFTC3) exists in both full-length membrane form and soluble secreted form, playing a modulatory role in aging, bone metabolism, and endothelial dysfunction." (PMID 34041260, 2021). "Recently, Klotho protein was found to be expressed in human aorta and coronary artery, which protects against endothelial dysfunction by increasing nitric oxide production." (PMID 32581850, 2020). "Previous studies using animal model were demonstrated that klotho protein protects the endothelial dysfunction through nitric oxide production by humoral pathways." (PMID 31398214, 2019). "The impact of klotho on vascular function remains poorly understood, but the protein seems relevant for vascular homeostasis, since mice with defective klotho gene exhibit endothelial dysfunction." (PMID 30773786, 2019). "Because Klotho and cerebral small vessel disease (SVD) are associated with ageing process and endothelial dysfunction, it is possible that Klotho has an association with cerebral SVD." (PMID 31398214, 2019). "So far, over 10 single nucleotide polymorphisms (SNPs) have been reported in human Klotho gene, and a growing body of evidence has shown the relationship between Klotho SNPs, susceptibility to CAD and endothelial dysfunction." (PMID 30547758, 2018). "Soluble klotho also prevents endothelial dysfunction by maintaining endothelial integrity and protecting against vascular permeability." (PMID 29250031, 2017). "Soluble Klotho has antiapoptotic effects on vascular endothelial cells and protects against endothelial dysfunction." (PMID 28194484, 2017). "In vivo, soluble Klotho deficiency is accompanied by activation of the renin angiotensin system (RAS) and endothelial dysfunction." (PMID 28194484, 2017). "Low Klotho levels has been suggested as a key factor in the development of endothelial dysfunction 23, which is involved in the initiation, progression and complications of athreosclerosis." (PMID 26538295, 2016). "In an atherosclerotic mouse model, the in vivo gene delivery of Klotho protects against endothelial dysfunction." (PMID 23431388, 2013). "Klotho deficiency, prevalent in CKD and aging, increases vascular susceptibility to phosphate toxicity and promotes osteogenic reprogramming of VSMCs through BMP-SMAD-RUNX2 signaling, endothelial dysfunction and arterial stiffening." (PMID 41303567, 2025).